CDC20 (cell division cycle 20)
Diseases named in the same sentence as CDC20 in open-access papers (continued):
Sharing a sentence is not in itself a finding about the gene and the disease.
glioblastoma (35 papers, 2011 to 2025). The most malignant astrocytic tumor (WHO grade IV). "We also observed that the promoter enrichment of H3K27ac and H3K9ac at CDC20 was more significant in glioblastoma and glioma cell lines than in healthy brain tissue." (PMID 40092489, 2025). "Glioblastoma, an aggressive form of brain cancer, shows elevated CDC20 expression, whereas its levels are reduced in LG tumors." (PMID 39795587, 2024). "Previous bioinformatical analysis suggested that GTF2E2 regulates the progression of glioblastoma by upregulating the level of the cell division cycle 20 (CDC20)." (PMID 34853466, 2022). "CDC20, a central regulator of the cell cycle in numerous cancers, was shown to have an essential role in the regulation of glioblastoma tumor-initiating cell proliferation, self-renewal, and survival." (PMID 36238156, 2022). "Their results also indicate the importance of CDC20 proto-oncogene expression in glioblastoma stem cells, as it plays an essential role in the regulation of proliferation, self-renewal, and survival of these cells." (PMID 36142793, 2022). "There was also evidence that supported the oncogenic role of CDC20 in glioblastoma via regulating SOX-2-dependent transcription." (PMID 35622386, 2022). "CDC20 expression is elevated in glioblastoma compared to low-grade gliomas, and patients with high CDC20-expressing GBMs in the Proneural subtype have significantly shorter overall survival." (PMID 35737702, 2022). "We established that Msi1 levels affect the expression of Bub1, Bub1B, MADL1 and CDC20 and Bub3 is a direct target of Msi1 in glioblastoma cells." (PMID 33804958, 2021). "It is also reported that expression level of CDC20 is correlated with the grade of glioblastoma and it is expressed at different levels in patients at different ages." (PMID 31001122, 2019). "For instance, patients with glioblastomas exhibited upregulation of Cdc20, while low-grade glioma patients have downregulation of Cdc20." (PMID 28165402, 2017). "For example, overexpression of Cdc20 was observed in glioblastomas, whereas Cdc20 was under-expressed in low-grade gliomas." (PMID 27626499, 2016). "In support of this concept, another study demonstrated that Cdc20 drives invasiveness and self-renewal in patient tumor-derived GSCs (glioblastoma stem-like cells) through pluripotenty related transcription factor SOX2." (PMID 27626499, 2016). "Multiple cancer types display increased CDC20 expression, but the role of CDC20 in glioblastoma generally and TICs, in particular, is unclear." (PMID 25938542, 2015). "Microarray studies have recently reported overexpression of CDC20 in various tumors, such as tumors of the oral cavity, stomach, brain (glioblastoma), urinary bladder, uterine cervix, and ovary." (PMID 23738901, 2013). "Furthermore, we found that among patients with melanoma, renal cell carcinoma, and glioblastoma who received anti-PD-1 immunotherapy, those with high CDC20 expression had poorer clinical outcomes." (PMID 40688701, 2025). "The regulatory mark of PRMT6-mediated asymmetric dimethylation of histones is a well-known mechanism that can either activate or repress gene expression, and our previous study demonstrated that PRMT6 can enhance the transcription of CDC20 in glioblastoma cells via H3R2me2a." (PMID 39043634, 2024). "In addition to its role in mitotic processes, CDC20 overexpression was found to enhance the invasive properties of glioblastoma stem cell-like cells." (PMID 39795587, 2024). "An overexpression and/or oncogenic role of CDC20 has been already described in a variety of human solid tumors including pancreas, breast, lung, prostate, gastric, colorectal, hepatocellular, kidney, ovarian cancer, osteosarcoma and glioblastoma." (PMID 35490245, 2022). "Our results identify a CDC20 signaling pathway that regulates chemo- and radiosensitivity in GSCs, with the potential for CDC20-targeted therapeutic strategies in the treatment of glioblastoma." (PMID 35737702, 2022).
glioblastoma (continued). "Furthermore, Cdc20 is highly expressed in multiple types of common human tumors including prostate, breast, cervical, glioblastoma, and ovarian tumors." (PMID 34527589, 2021). "Cdc20 has been reported to be widely expressed in glioblastomas tissues." (PMID 32322669, 2020). "CDC20 was highly expressed in glioblastomas, relative to normal brain and lower grade glioma." (PMID 25938542, 2015). "Cdc20 and c-Myc are commonly overexpressed in a broad spectrum of cancers, including glioblastoma (GBM)." (PMID 26993778, 2016). "The E3 ligase CDC20 regulates SOX2 protein level and transcription in glioblastoma, affecting invasion and self-renewal properties." (PMID 33613844, 2021). "Last, FOXM1 stimulates self-renewal, tumorigenicity and invasiveness of glioblastoma stem-like cells by transactivating a number of molecules, including IPO7 (importing-7), CDC20, PDGF-A, ANXA1, MMP-2 and VEGF." (PMID 27259253, 2016). "In addition, in colorectal cancer, the activation of Wnt/β-catenin signaling during G1 phase, is controlled by CDC20-mediated degradation of conduction and a CDC20-APC/SOX2 axis regulates invasiveness and self-renewal of glioblastoma stem-like cells." (PMID 35490245, 2022). "With the development of specific CDC20 small molecule inhibitors, such as TAME and Apcin, our study may inform the development of novel therapeutic paradigms for glioblastoma and other advanced cancers." (PMID 25938542, 2015). "However, correlations of SAC gene expression with aggressiveness have not been reported for glioma except for CDC20 that has higher expression in glioblastoma than in low grade glioma." (PMID 22022424, 2011).
glioma (35 papers, 2011 to 2025). A benign or malignant brain and spinal cord tumor that arises from glial cells (astrocytes, oligodendrocytes, ependymal cells). "A 20-gene CDC20-associated mitotic signature (CDC20-M), comprising genes controlling chromosome segregation and mitotic checkpoints identifies gliomas with high genomic instability and TMZ resistance." (PMID 41511341, 2025). "This study suggests the potential roles of a novel hypoxia‐associated CDC20+KIF20A+PTTG1+ cell subpopulation in glioma progression." (PMID 40047299, 2025). "CDC20 overexpression and its associated gene modules were characteristically elevated, signifying increased genomic instability in gliomas." (PMID 35774141, 2022). "CDC20 increased expression has been observed in high-grade gliomas and linked to poor patient survival while its knockdown reduced invasion, self-renewal, proliferation of GSCs and impaired tumor initiation." (PMID 33804958, 2021). "CDC20 drives the aggressiveness and self-renewal of gliomas and is associated with genomic instability." (PMID 33914773, 2021). "To investigate the causal role of c-Myc and Cdc20 in glioma development, we induced c-Myc and Cdc20 expression in our RCAS/Ntv-a glia-specific mouse model." (PMID 26993778, 2016). "To investigate the causal role of c-Myc and Cdc20 in glioma development, we injected Ntv-a transgenic mice with DF1 cells that produced RCAS-c-Myc or RCAS-Cdc20." (PMID 26993778, 2016). "Higher CDC20 expression correlated with shorter survival of glioma patients, befitting its association with tumor grade." (PMID 25938542, 2015). "We identified a unique CDC20+KIF20A+PTTG1+ high‐risk glioma cell subpopulation probably necessary for glioma progression of LGG/GBM transformation, which was further explored in multiple cohorts and validated in samples by immunohistochemistry and multiplex immunofluorescence assays." (PMID 40047299, 2025). "Hence, these results hint that CDC20+KIF20A+PTTG1+ high‐risk glioma cell subpopulation was specifically associated with hypoxia, which may drive this cell subpopulation predominantly via regulating its No.1 marker gene CDC20." (PMID 40047299, 2025). "Additionally, gliomas with high levels of CDC20 are associated with a poor prognosis." (PMID 40092489, 2025). "Therefore, our data suggests that CDC20 downregulation could be one of the mechanisms for the decreased cell viability caused by compound 331 in glioma cells." (PMID 26153143, 2015). "HMGN2 binds to histones and promotes the stability of H3K27ac acetylation in the cell division cycle 20 (CDC20) promoter region, enhancing the transcriptional activity of CDC20 and increasing the proliferation of glioma cells." (PMID 40092489, 2025). "Higher CDC20 expression has been observed in GBM compared with low‐grade gliomas, with patients with higher‐CDC20‐expressing GBM of the proneural subtype exhibiting significantly shorter overall survival." (PMID 40439120, 2025). "The CDC20 expression in the human glioma tissues was also up-regulated parallel to the tumor grade, consistent with mRNA sequencing data analysis." (PMID 40092489, 2025). "In conclusion, alterations in the cell cycle induced by CDC20 play an important role in glioma cell proliferation resulting from HMGN2 knockdown." (PMID 40092489, 2025). "Higher CDC20 expression has been observed in GBM than in low‐grade gliomas, with patients with higher CDC20 expression and GBM of the proneural subtype exhibiting significantly shorter overall survival." (PMID 40439120, 2025). "Our experiments further hint that this cell subpopulation, in particular its marker gene CDC20, was higher in the hypoxia core region of glioma PDOs, suggesting that CDC20 plays a vital role in the glioma hypoxic microenvironment." (PMID 40047299, 2025). "The disease-free survival curve indicated that CDC20 expression was negatively correlated with the survival time of glioma patients." (PMID 40092489, 2025).
glioma (continued). "CDC20+KIF20A+PTTG1+ glioma cell subpopulation remains relative higher hypoxia level than other glioma cells in each time point, and increased during long‐term gliomagenesis." (PMID 40047299, 2025). "In conclusion, these findings suggest that the CDC20+KIF20A+PTTG1+ cell subpopulation is critical to glioma progression." (PMID 40047299, 2025). "Targeting CDC20 expression inhibits the malignant progression of glioma; thus, CDC20 is regarded as an attractive target for glioma treatment." (PMID 40439120, 2025). "The rescue experiment further showed that HMGN2 knockdown regulated the cell cycle by decreasing the level of CDC20, consequently attenuating the proliferative ability of glioma cells." (PMID 40092489, 2025). "Taken together, these results demonstrated that HMGN2 and CDC20 expression were up-regulated in human glioma tissues, and we observed a clear correlation between CDC20 and HMGN2 expression." (PMID 40092489, 2025). "Existing studies have shown that PRMT6 is upregulated in gliomas and regulates the mitosis and tumorigenicity of glioblastoma stem cells by methylating RCC1, or promotes the proliferation of glioma cells by transcriptionally activating CDC20." (PMID 38637831, 2024). "In glioma, CDC20 has been identified as an oncogenic factor mediating tumor cell growth, invasion, and chemosensitivity." (PMID 36792756, 2023). "Targeting CDC20 inhibits the malignant progression of glioma and CDC20 is considered an attractive target for therapeutic intervention." (PMID 36792756, 2023). "Jeremy Rich’s team identified an increased expression of CDC20 in GBM compared to lower grade gliomas and healthy brain tissue." (PMID 36142793, 2022). "Genes associated with the neuronal differentiation pathway (Pcsk9, Runx1, Cebpb, Fzd4, Wnt7a, Ascl1, Fzd2, Edn3, Olig2, and Gpc2), gliomas (Shc1, Cdk4, E2f2, and Ccnd1), and cell cycle (Bub1b, Bub, Ccnb1, Ccnb2, and Cdc20) were significantly downregulated." (PMID 36147849, 2022). "CDC20 expression is increased in a variety of tumors and associated with temozolomide (TMZ) resistance in glioma cells." (PMID 34753395, 2021). "Our previous study found that CDC20 expression increased with the malignant progression of glioma and led to poor patient prognosis." (PMID 34753395, 2021). "Our results showed that 25 of the differentially expressed URGs were related to survival in glioma patients; six genes, CDC20, UBE3C, WDR62, DTL, HOXB4, and TRIM38, were statistically significant with an AUC value greater than 0.7." (PMID 33914773, 2021). "In fact, it has been shown that the expression of CDC20 plays an important role in TMZ resistance in glioma cells." (PMID 34753395, 2021). "Downregulation of Cdc20 induced cell apoptosis in glioma cells and abrogated EPIC1-mediated inhibition of cell apoptosis in glioma." (PMID 32322669, 2020). "In line with this, overexpression of Cdc20 reversed the EPIC1-mediated tumor progression in glioma cells." (PMID 32322669, 2020). "To explore the mechanism of EPIC1-mediated tumorigenesis in glioma cells, we examined the expression level of Cdc20 in SNB19, T98G, and U97MG cells after EPIC1 modulation using western blotting analysis." (PMID 32322669, 2020). "Our data showed that downregulation of EPIC1 by siRNA transfection reduced the expression of Cdc20 in three glioma cell lines." (PMID 32322669, 2020). "Our previous study has shown that Cdc20 knockdown in TMZ-resistant cells increased the sensitivity of cells to TMZ in glioma cells." (PMID 32322669, 2020). "Consistently, overexpression of Cdc20 abrogated TMZ sensitivity due to downregulation of EPIC1 in glioma cells." (PMID 32322669, 2020). "One study showed that Cdc20 was preferentially existed in tumorigenic glioma tumor initiating cells (TICs)." (PMID 32322669, 2020). "Overexpression of Cdc20 reversed the EPIC1 siRNA-mediated inhibition of cell viability in glioma cells." (PMID 32322669, 2020).
glioma (continued). "In glioma, knockdown of CDC20 enhanced the drug sensitivity of glioma cells to temozolomide, suggesting that CDC20 inactivation contributed human cancer control." (PMID 31106147, 2019). "Our data suggested that rottlerin inhibited cell motility partly through inhibition of Cdc20 in glioma cells." (PMID 27626499, 2016). "Recently, Cdc20 was reported to be a key factor in maintaining tumorigenic glioma tumor initiating cells through degradation of p21 and regulation of Cdc25C (cell division cycle 25C), c-Myc, and Survivin." (PMID 27626499, 2016). "More importantly, we observed that Cdc20 overexpression abrogated cell growth inhibition induced by rottlerin in glioma cells." (PMID 27626499, 2016). "Cdc20 shRNA treatment led to more apoptotic cells induced by rottlerin compared with rottlerin alone or Cdc20 shRNA transfection alone in glioma cells." (PMID 27626499, 2016). "In the present study, we identified that rottlerin inhibited Cdc20 expression, resulting in inhibition of tumorigenesis in glioma." (PMID 27626499, 2016). "Altogether, Cdc20 plays a pivotal role in regulation of cell growth, migration and invasion in glioma cells." (PMID 27626499, 2016). "Our Western blotting analysis demonstrated that Cdc20 shRNA enhanced rottlerin-mediated inhibition of Cdc20 in glioma cells." (PMID 27626499, 2016). "Our results further showed that Cdc20 overexpression enhanced cell migration and invasion in glioma cells, while downregulation of Cdc20 retarded cell motility." (PMID 27626499, 2016). "To further determine the role of Cdc20 in rottlerin-mediated tumor suppressive activity, we depleted Cdc20 by its shRNA in glioma cells." (PMID 27626499, 2016). "We also found that overexpression of Cdc20 enhanced glioma cell proliferation, whereas depletion of Cdc20 suppressed cell growth in glioma cells." (PMID 27626499, 2016). "RT-PCR and Western blotting analysis were used to detect the expression of Cdc20 in glioma cells after rottlerin treatment for 72 hours." (PMID 27626499, 2016). "Mechanistically, the expression of Cdc20 oncoprotein was measured by the RT-PCR and Western blot analysis in glioma cells treated with rottlerin." (PMID 27626499, 2016). "While Huang and co-workers found that heat shock factor 1 (HSF1) regulates FOXM1 in glioma with changes in cell cycle proteins, including CDC20, our results provides the first direct evidence that FOXM1 maintains TICs via regulation the expression of CDC20." (PMID 25938542, 2015). "Previous reports of CDC20 expression in glioma demonstrated a positive correlation tumor grade, similar to our in silico findings." (PMID 25938542, 2015). "The downregulation of CDC20 induced mitotic catastrophe in glioma cells further leads to cell death of glioma cells." (PMID 26153143, 2015). "Our data suggests that compound 331 has the potential to selectively induce glioma cell death by selectively upregulating miR-494 and downregulating CDC20 in glioma cells." (PMID 26153143, 2015). "In conclusion, compound 331 downregulated CDC20 in glioma cells and ensued in the accumulation of multi-nucleus cells, G2/M arrest, and cell apoptosis." (PMID 26153143, 2015). "Western blot and RT-PCR data confirmed that CDC20 was downregulated by compound 331 treatment both in vitro in cultured glioma cells (20 μM, 48 h) and in vivo in nude mice." (PMID 26153143, 2015). "Our data suggests that compound 331 induces mitotic catastrophe, which results in apoptosis by downregulating CDC20 in glioma cells." (PMID 26153143, 2015). "CDC20 is an important regulator of the cell cycle so we performed an in silico analysis of CDC20 expression in glioma patients." (PMID 25938542, 2015). "Moreover, spatial atlas of GBM also showed that relative higher hypoxia level in spots of CDC20+KIF20A+PTTG1+ glioma cell subpopulation." (PMID 40047299, 2025).